GYPC (glycophorin C (Gerbich blood group))
Description:
This protein is a minor sialoglycoprotein in human erythrocyte membranes. The blood group Gerbich antigens and receptors for Plasmodium falciparum merozoites are most likely located within the extracellular domain. Glycophorin-C plays an important role in regulating the stability of red cells.
Synonyms: GPD; CD236; GPC; GYPD; Ge; CD236R; PAS-2; PAS-2'
Tractability: Antibody: its Gene Ontology location is reachable by antibodies, with high confidence; UniProt places it where antibodies can reach, with medium confidence; UniProt predicts a signal peptide or a membrane-spanning region; the Human Protein Atlas places it where antibodies can reach. PROTAC: ubiquitination databases record sites on it.
Gene: Protein-coding gene on chromosome 2 (126,655,938 to 126,696,667, forward strand). Ensembl gene ENSG00000136732.
Subcellular location: Cell membrane
Subcellular location (Human Protein Atlas): Plasma membrane
Pathways (Reactome):
Hemostasis: Cell surface interactions at the vascular wall
Gene Ontology:
Molecular function: protein binding
Biological process: response to fluid shear stress
Cellular component: cortical cytoskeleton; membrane; plasma membrane
Genetic constraint (gnomAD): Loss-of-function variants: 8 observed, 7.52 expected, observed/expected ratio (o/e) 1.06, 90% interval 0.62 to 1.77. That is too few expected variants to judge how well the gene tolerates losing a copy. Missense variants: 173 observed, 139 expected, observed/expected ratio (o/e) 1.24, 90% interval 1.1 to 1.41. Synonymous variants: 59 observed, 53.35 expected, observed/expected ratio (o/e) 1.11, 90% interval 0.9 to 1.37.
Homologues: Orthologues: chimpanzee GYPC (91% identical), mouse Gypc (53% identical), pig GYPC (53% identical), rat Gypc (51% identical), dog GYPC (44% identical), guinea pig Gypc (44% identical), zebrafish gypc (41% identical), tropical clawed frog gypc (40% identical).
Diseases named in the same sentence as GYPC in open-access papers:
GYPC is named in the same sentence as 26 diseases in open-access papers, as found by Europe PMC text mining. Sharing a sentence is not in itself a finding about the gene and the disease. The quoted sentences say what the papers report.
endometrial cancer (6 papers, 2022 to 2025). Primary or metastatic malignant neoplasm involving the endometrium (mucous membrane that lines the endometrial cavity). "We have recently developed and validated the WID‐qEC test, which assesses DNA methylation of ZSCAN12 and GYPC via real‐time PCR, to triage women with symptoms suggestive of endometrial cancer using ThinPrep‐based liquid cytology samples." (PMID 36056582, 2023). "Utilizing cervical scrapings as a potential genetic material, coupled with the use of DNA hypermethylation in specific genes, including CDO1, CELF4, BHLHE22, POU4F3, MAGI2, CADM1, MAL, miR124-2, ZSCAN12, and GYPC, has been investigated for endometrial cancer detection." (PMID 41008854, 2025). "We describe the Women's cancer risk IDentification – quantitative polymerase chain reaction test for Endometrial Cancer (WID-qEC), a three-marker test that evaluates DNA methylation in gene regions of GYPC and ZSCAN12." (PMID 36001862, 2022).
malaria (6 papers, 2008 to 2020). Malaria is a serious and sometimes fatal disease caused by a parasite that commonly infects a certain type of mosquito which feeds on humans. "In humans, GYPC has been associated with malaria susceptibility, and predicted to have undergone recent positive selection." (PMID 18670650, 2008). "Nevertheless, alleles of different well-known genes that are likely to have undergone selection by malaria have been identified using this approach, such as GYPC (glycophorin C), ABO (ABO blood group), and SLC4A1 (erythrocyte membrane protein band)." (PMID 24005574, 2014).
breast carcinoma (4 papers, 2011 to 2022). "A recent study suggested GYPC can be used as a biomarker of breast cancer." (PMID 32795291, 2020). "In another study, GYPC gene expression patterns (using ONCOMINE, GENT2, and GTX2 networks) in breast cancer and patient survival datasets were analyzed using several bioinformatics tools (including Oncomine)." (PMID 36430403, 2022).
elliptocytosis (2 papers, 2011 to 2022). "A decrease in GYPC levels is observed in cases of ovalocytosis, a rare hereditary red cell membrane defect characterized by the presence of oval erythrocytes." (PMID 36065290, 2022).
lung adenocarcinoma (2 papers, 2020 to 2023). A carcinoma that arises from the lung and is characterized by the presence of malignant glandular epithelial cells. "Compared with normal BEAS-2B cells, the expression levels of GYPC and SLIT2 in four human lung adenocarcinoma cell lines (PC9, A549, H1975 and H1299) were up-regulated, while NME1 expression was down-regulated." (PMID 32795291, 2020).
acute lymphoblastic leukemia (1 paper, 2020). Leukemia with an acute onset, characterized by the presence of lymphoblasts in the bone marrow and the peripheral blood. "Increased GYPC gene expression was also reported to correlate with a worse outcome in childhood acute lymphoblastic leukemia." (PMID 32795291, 2020).
anemia (1 paper, 2020). A reduction in the number of red blood cells, the amount of hemoglobin, and/or the volume of packed red blood cells. "Interestingly, two of the six modules (network modules 1 and 4) contained genes that code for proteins expressed in erythrocytes or other blood components (HBM, RHD, GYPA, GYPC, CA1), or have been implicated in blood-associated diseases like anemia (GYPA)." (PMID 32728112, 2020).
bladder cancer (1 paper, 2022). "Few studies had reported that the six genes (TBXAS1, GYPC, HPGDS, GAB3, ADORA3, and FOLR2) had strong correlation with bladder cancer." (PMID 36275756, 2022).
lung carcinoma (1 paper, 2020). "GSEA enrichment analysis indicated that GYPC was significantly associated with the JAK/STAT and cell adhesion signaling pathways which are essential to lung cancer progression and migration." (PMID 32795291, 2020). "However, there is limited evidence for the function of GYPC in the majority of solid tumors, especially in lung cancer." (PMID 32795291, 2020). "The expression levels of GYPC, NME1 and SLIT2 in S30 cells and lung cancer cell lines were validated by quantitative PCR, immunofluorescence, and western blot assays." (PMID 32795291, 2020).
Obesity (1 paper, 2017). Accumulation of substantial excess body fat. "In race/ethnic-specific analyses, we identified a number of genes related to obesity (GNPDA2, ZNF664-FAM101A, PFKP, SAMD4A), glycosylation (GYPC, FUT10), and carbohydrate metabolism (GNPDA2, PFKP, SLC45A)." (PMID 28521775, 2017).
infection (8 papers, 2009 to 2026). The state of being infected such as from the introduction of a foreign agent such as serum, vaccine, antigenic substance or organism. "The results showed that all highly glycosylated proteins, with the exception of GYPC, which has the shortest ectodomain, had an inhibitory effect on infection." (PMID 41147561, 2025). "Glycophorins (GYPA, GYPB, GYPC) bind to Plasmodium surface proteins, and GYPC-non expressing individuals show reduced invasion of erythrocytes, and are protected from infection." (PMID 26658699, 2015). "Confocal immunofluorescence microscopy confirmed MSP1 labelling characteristic of rings at 6 hours post-infection and the presence of some schizonts at the end of the 24 h cycle in the KO cell lines for both genes, though the frequency and size of the parasites is smaller in the GYPC-/- cell line." (PMID 27362409, 2016).
tumours (7 papers, 2019 to 2023). "Apart from being highly expressed in red blood cells, the potential mechanisms by which GYPC exerts its protective role in these types of tumours remain to be elucidated." (PMID 37612734, 2023). "The expression levels of GIMAP1 and GYPC were significantly correlated to the tumor grade and only GYPC was significantly correlated to the tumor histology in EC." (PMID 33869285, 2021). "characterized “tumor-matching” T cells in the peripheral blood (i.e., T cells in the blood expressing tumor-specific TCRs) as cells that expressed a more effector phenotype with a decreased expression of genes GYPC, CCR7, LTB, and FLT3LG." (PMID 37122719, 2023). "In the perspective of tumor grade, GIMAP1 showed the lowest expression in high grade while GYPC showed the lowest expression in G3." (PMID 33869285, 2021). "Moreover, five genes, including the SLC12A4, SLIT3, GYPC, TSPAN4, CYYBRD1, CYB5R3, and FBLN5 were identified as co-expressed in the healthy and tumor tissue groups." (PMID 37365287, 2023). "The eight probes extracted from the RFECV method showing discriminative power between tumour and nontumour samples included cg17105014 (GYPC), cg23273897 (MME), cg22083047 (PRICKLE2), cg09396217 (ANGPT1), cg01049530 (BMP3), cg18237405 (CPNE5), cg12741420 (IRF4) and cg11754206 (KCNB2)." (PMID 36779430, 2023).
cancer (5 papers, 2012 to 2025). A tumor composed of atypical neoplastic, often pleomorphic cells that invade other tissues. "Overexpression of methylation and underexpression of mRNA in Glycophorin C (GYPC) have been observed in several cancers, carrying significant diagnostic and prognostic implications." (PMID 40313561, 2025).
GYPC also shares sentences with these, for which no sentence is quoted: acute myeloid leukaemia (1 paper); atherosclerosis (1); calcification (1); cholestasis (1); colon cancer (1); glioblastoma (1); hemorrhage (1); Lassa fever (1); liver fibrosis (1); ovarian carcinoma (1); sandfly fever (1); steatosis (1); stomach cancer (1).